IL10 (interleukin 10)
Diseases named in the same sentence as IL10 in open-access papers (continued):
Sharing a sentence is not in itself a finding about the gene and the disease.
Sciatica (1 paper, 2021). Pain in the lower back and hip radiating in the distribution of the sciatic nerve. "Previous studies have reported serum inflammatory biomarkers of sciatica, and these include TNF-α, IL-4, IL-6, IL-8, IL-10, IL-17, IL-21, T helper lymphocytes 17, phospholipase A2, C-reactive protein, C-X3-C motif ligand 1, C-C motif ligand 2 and mast cell proteinase-1." (PMID 33535986, 2021).
sclerosing cholangitis (1 paper, 2024). A chronic, autoimmune inflammatory liver disorder characterized by narrowing and scarring of the lumen of the bile ducts. "Next, we aimed to validate our observation in Il10−/−Mdr2−/− mice using a second model of experimental sclerosing cholangitis." (PMID 38839272, 2024). "DDC diet-induced sclerosing cholangitis in Il10−/− mice as determined by blood transaminase levels and fibrosis development." (PMID 38839272, 2024). "As expected, Il10−/−Mdr2−/− mice, but not Il10−/− mice, developed sclerosing cholangitis based on increased transaminase AST and ALT levels, and fibrosis score." (PMID 38839272, 2024).
scrapie (1 paper, 2022). A fatal disease of the nervous system in sheep and goats, characterized by pruritus, debility, and locomotor incoordination. "The analysis of cytokine levels revealed the overexpression of TGF-β, IL-10, and IL-6 in the thalamus of the scrapie-infected versus control sheep, but no alterations in the hippocampus." (PMID 35408945, 2022).
seborrheic dermatitis (1 paper, 2026). A chronic, inflammatory skin disorder that affects the scalp, central face and skin folds; it is characterized by scaling and itching. "The authors concluded that seborrheic dermatitis could be due to the overexpression of IL-10, which downregulated the production of IL-2 and IFN-γ and promoted the synthesis of IgA and IgG." (PMID 41602867, 2026).
secondary-progressive MS (1 paper, 2022). "A significantly lower level of IL-10 production by B cells stimulated in the presence of CD40L was found in the groups with relapsing-remitting and secondary-progressive MS as compared with HDs." (PMID 36052064, 2022).
serous ovarian cancer (1 paper, 2021). "Another report implies that Foxp3+ regulatory cells are recruited to the tumor microenvironment of high grade serous ovarian cancer and act through immunomodulatory cytokines such as IL-10 and TGF-β." (PMID 34181334, 2021).
sexual dysfunction (1 paper, 2024). Disturbances in sexual desire and the psychophysiologic changes that characterize the sexual response cycle and cause marked distress and interpersonal difficulty. "Alterations in the molecular profile of IL-8, BDNF, and IL-10 provide insights into the mechanisms underlying sexual dysfunction in these patients." (PMID 39796020, 2024).
sexually transmitted infections (1 paper, 2016). "Increased IL‐10 levels in the endocervix have been associated with the presence of sexually transmitted infections, which are in turn linked to increased HIV acquisition." (PMID 27401588, 2016).
sialadenitis (1 paper, 2023). Sialadenitis is an infection of the salivary glands. "Here, we revealed that exogenous VIP upregulated the levels of IL‐2 and IL‐10, as well as alleviated sialadenitis with dry mouth." (PMID 37506142, 2023).
skin abscess (1 paper, 2024). "Interestingly, the inhibition of IL-10 during the vaccination process also led to a substantial increase in production of IL-1β within the skin abscess." (PMID 38973612, 2024).
Sleep apnea (1 paper, 2023). An intermittent cessation of airflow at the mouth and nose during sleep is known as sleep apnea. "The present investigation is unique in its comprehensive analysis of IL-6, IL-8, IL-10, TNF-α, CRP, and S100B in a single cohort of sleep apnea patients compared to non-OSA controls in both serum and plasma." (PMID 37762178, 2023).
Sm (1 paper, 2018). "Thus, the possible mechanism by which Sm infection suppresses these HIV-specific cellular and humoral responses appear to involve the deposition of SmE in the tissues, which stimulates increased production of IL-4 and IL-10 with concomitant polarization of Th2 immune responses." (PMID 30048550, 2018).
social phobia (1 paper, 2018). An anxiety disorder characterized by an intense, irrational fear of one or more social or performance situations in which the individual believes that he or she will be scrutinized by others. "Change in IL-10 levels with treatment was significantly positively correlated with change in ABC social withdrawal scores (0.44, p = 0.05) and showed a trend (0.41, p = 0.06) toward a positive correlation with change in CASI-social phobia score." (PMID 30498564, 2018).
soft tissue sarcoma (1 paper, 2024). A malignant neoplasm arising from muscle tissue, adipose tissue, blood vessels, fibrous tissue, or other supportive tissues excluding the bones. "A previous study compared the levels of the cytokines IL-12p70 and IL-10 in 59 children (aged 2–15 years) with soft tissue sarcoma and showed that those in remission had increased IL-12 production and decreased IL-10 levels." (PMID 38745774, 2024).
Spastic tetraplegia (1 paper, 2018). Spastic paralysis affecting all four limbs. "In the current study, we found that IL-10 protein levels were increased in CP patients, especially in spastic tetraplegia, the most severe subtype of CP patients." (PMID 29623066, 2018).
Spinocerebellar atrophy (1 paper, 2018). Atrophy affecting the cerebellum and the spinocerebellar tracts of the spinal cord. "Second, both pro-inflammatory and anti-inflammatory cytokines (IL-10, IL-4, IL-5, and IL-13) were present in most disorders studied, but the IL-10 concentration was reduced in the degenerative disorders spinocerebellar atrophy (SCA) and MSA-C." (PMID 29670611, 2018).
staphylococcal pneumonia (1 paper, 2013). Pneumonia caused by infections with bacteria of the genus staphylococcus, usually with staphylococcus aureus. "IL-10 is an important mediator of the enhanced susceptibility to staphylococcal pneumonia." (PMID 23369570, 2013).
stress-related disorder (1 paper, 2015). Stress-related disorders are mental health disorders that are a result of an atypical response to both short and long-term anxiety due to physical, mental, or emotional stress. "With a further study that attempts to elucidate the underlying mechanism of IL-4 and IL-10 and neuroimmune response by microglia, therapeutic intervention for stress-related disorders might be optimized." (PMID 26521132, 2015).
Susac syndrome (1 paper, 2021). Susac syndrome (SS) is a rare disorder characterized by the triad of central nervous system (CNS) dysfunction, branch retinal artery occlusions (BRAOs) and sensorineural hearing loss (SNHL). "An increase in TNF⍺ and reduction of IL-10, would also support a pro-inflammatory immune-phenotype, and the development of Susac’s syndrome." (PMID 34625019, 2021).
systemic vasculitis (1 paper, 2019). "However, AAV patients with early systemic vasculitis displayed higher serum IL-10 than healthy controls (51.2 ± 40.7 vs. 4.6 ± 4.4 pg/ml; p = 0.005)." (PMID 31286195, 2019).
Taenia infection (1 paper, 2015). "Taenia infection decreased systemic levels of proinflammatory cytokines while increasing levels of IL-4 and IL-10, and the inflammatory infiltrate into the colon was also markedly reduced." (PMID 26090422, 2015).
tapeworm infection (1 paper, 2022). "In addition, the gene expression profile of the pro- and anti-inflammatory cytokines (TNF-α, IL-1β, IL-6 and IL-10) was evaluated by Real-Time PCR to determine the immune response within the CNS to the tapeworm infection." (PMID 35286352, 2022).
testicular tumors (1 paper, 2017). "Bialas and colleagues in 2009 investigated the role of IL-6, IL-10, TNF-α-, TNFR1, and TNFR2 in the processes of normal and abnormal spermatogenesis as well as testicular tumors using Real-Time PCR technique." (PMID 29082371, 2017).
thymus (1 paper, 2021). "Mechanistically, the flo8 mutant-induced Dectin-2/CARD9-mediated IL-10 production in DCs and macrophages to block thymus atrophy by inhibiting the C. albicans-induced apoptosis of thymic T cells, which facilitated the continuous output of naive T cells from the thymus to the spleen." (PMID 33154574, 2021).
thyrotoxicosis (1 paper, 2009). A hypermetabolic syndrome caused by the elevation of thyroid hormone levels in the serum. "Several previous reports have tried to address thecontribution of thyrotoxicosis to the rise in inflammatory cytokines such as IL-1,IL-6, IL-10, and TNF-alpha." (PMID 19343192, 2009). "We hypothesized that reactive oxygen intermediates, that were induced by thyrotoxicosis, act as a signal for the release of cytokines like IL-6, IL-10, and TNF-alpha." (PMID 19343192, 2009). "It provides new insights into the roleof IL-10 and TNF-alpha in thyrotoxicosis." (PMID 19343192, 2009).
tick-borne encephalitis (1 paper, 2017). Tick-borne encephalitis is caused by an arbovirus of the Flaviviridae family (tick-borne encephalitis virus, TBEV), transmitted principally by the bite of the Ixodes ricinus tick. "It has been shown in the Russian population that five SNPs in OAS2 and OAS3 genes, as well as two SNPs in IFNL3/IL28B gene and polymorphisms in the TLR3, CD209, and IL10 genes were associated with predisposition to severe forms of tick-borne encephalitis." (PMID 29297316, 2017). "Using STRING we found that IL10 interacted physically with alpha-2-macroglobulin (A2M) that was also found to be elevated in patients with the meningeal and focal forms of tick-borne encephalitis." (PMID 29297316, 2017).
tongue (1 paper, 2022). "However, significantly higher percentage of IL-10-producing CD8+ T cells was observed in MLNs of tongue SCC in comparison with nMLNs (P = 0.042)." (PMID 36376825, 2022).
tonsil infection (1 paper, 2021). "The human tonsil infection model that we employed here has been previously shown to support productive HIV infection, cell death, and release of cytokines such as IL-1β and IL-10, which is similar to an HIV-induced inflammation in humans." (PMID 34446704, 2021).
tonsillar cancer (1 paper, 2018). "In further support of an immunosuppressive profile, the IL-10 signaling pathway was an enrichment hit for CD1c+ mDCs in tonsillar cancer." (PMID 29795118, 2018).
toxic epidermal necrolysis (1 paper, 2006). Toxic epidermal necrolysis (TEN) is an acute and severe skin disease with clinical and histological features characterized by the destruction and detachment of the skin epithelium and mucous membranes. "Detectable amounts of IL-4 and IL-10 and ofsoluble IL-2R have been measured in the blister fluid of patientswith toxic epidermal necrolysis, a disease in which the earlyparticipation of activated CD8+ T lymphocytes play animportant role." (PMID 16864900, 2006).
toxicity (1 paper, 2023). The degree to which an agent can damage an organism. "In conclusion, DOXO-induced heart toxicity displayed a marked lowering in HW/BW ratio, significant elevations in the activities of CPK, AST, and LDH enzymes, significant elevations in Na, K, TNF-α, IL-10, MDA, and NO levels, and significant drops in levels of GSH and SOD." (PMID 36967438, 2023).
Tracheomalacia (1 paper, 2019). "The expression levels of IL-6, IL-8, and IL-10 were significantly higher in inpatients with AVP compared to children hospitalized with tracheomalacia or MPP." (PMID 31316955, 2019). "The expressions of IL-5, IL-6, and IL-10 in BALF of AVP were significantly higher than those of MPP and tracheomalacia patients (p-value: 0.016, <0.001, <0.001, respectively)." (PMID 31316955, 2019).
traumatic stress disorder (1 paper, 2025). "We were unable to show changes in the circulating concentrations of IL10, IL6, and TNFα after stress, as previously reported in health volunteers, and for IL6 in patients with post‐traumatic stress disorder undergoing stress." (PMID 40584280, 2025).
Tumor Lysis Syndrome (1 paper, 2021). a group of metabolic abnormalities that can occur as a complication during the treatment of cancer, most commonly after the treatment of lymphomas and leukemias. "However, there were still 4 out 18 patients showing grade 3 CRS, which might be attributed to tumor lysis syndrome and other cytokines that were significantly elevated during CART therapy, which might involve GM-CSF, G-CSF, MCP-1, TNFA, MIP-1, IL8, IL13, and IL10." (PMID 34518515, 2021).
type 1 autoimmune diabetes (1 paper, 2022). "It has been reported that SEA can protect against type 1 autoimmune diabetes via increasing Foxp3 expression in a TGF-β-dependent manner, along with upregulating C-type lectins, IL-10, and IL-2 on dendritic cells (DC)." (PMID 36304936, 2022).
uterine fibroids (1 paper, 2025). "Inflammation plays a critical role in the development of uterine fibroids, characterized by elevated expression levels of pro-inflammatory and inflammatory cytokines such as interleukin-1, interleukin-6, interleukin-10, TNF-α, and TGF-β." (PMID 39911698, 2025).
Veno-occlusive disease (1 paper, 2015). "Veno-occlusive disease was accompanied by a significant increase in levels of IL-6, IL-8 and TNF-α.Graft-versus-Host disease was associated with a significant increase of IL-10, sIL-2R, IL-6 and TNF-α, depending on the respective stage or grade." (PMID 26315105, 2015).
Vestibular schwannoma (1 paper, 2024). A vestibular schwannoma (also known as acoustic neuroma, acoustic neurinoma, or acoustic neurilemoma) is a benign, usually slow-growing tumor that develops from the VIIIth cranial nerve supplying the inner ear. "In addition, the levels of proinflammatory/proallergic cytokines (IL-4, IL-5, IL-10, and IL-13) were higher in the macula, ampulla, and endolymphatic sac dissected from patients with MD than in the specimens from patients with vestibular schwannoma." (PMID 38595846, 2024).
Vitamin D (1 paper, 2014). "Vitamin D insufficiency did not affect total lung or bronchoalveolar lavage (BAL) cells, but did result in a significant increase in pulmonary CD3+CD4+T1ST2+ Th2 cells and a reduction in CD4+IL-10+ T regulatory cells." (PMID 24943330, 2014).
Weil's disease (1 paper, 2024). A jauncice caused by severe leptospirosis. "Patients with Weil’s disease may present with a cytokine storm characterized by high levels of IL-6, IL-10, and tumor necrosis factor-alpha (TNF-α)." (PMID 38398036, 2024).
Whipple disease (1 paper, 2015). A systemic infection caused by the Gram-positive bacterium Tropheryma whipplei. "Interestingly, in Whipple’s disease, Tropheryma Whipplei accumulate in duodenal macrophages which express a similar phenotype to the E. coli-laden macrophages in this study (high IL-10, CD163) which is thought to facilitate their persistence." (PMID 26137941, 2015).
whipworm infection (1 paper, 2019). "Here, the IL-10 signalling deficient mice serve as a model to understand how polymorphisms in either the cytokine or the receptor impact the responses to whipworm infections." (PMID 30640950, 2019). "Moreover, breakdown of the epithelial barrier after whipworm infection in IL-10, IL-10Rα and IL-10Rβ-deficient mice, allows the translocation of these opportunistic pathogens or their excretory products to the liver causing organ failure and lethal disease." (PMID 30640950, 2019). "Dysfunction of IL-10 signalling may trigger the development of dysbiosis and pathology during whipworm infection of weaning pigs and children as polymorphisms in the IL-10 gene in humans have been associated with T. trichiura infection." (PMID 30640950, 2019). "Specifically, IL-10 promotes host resistance and survival to whipworm infection, with IL-10 deficiency leading to morbidity and mortality that may be due to a breakdown of the epithelial barrier and the outgrowth of opportunistic bacteria." (PMID 30640950, 2019). "invade the caecal epithelium of IL-10 signalling-deficient mice upon whipworm infection." (PMID 30640950, 2019). "Liver pathology appears to be caused by dissemination of gut bacteria or their products to the liver, upon breakdown of the caecal epithelial barrier due to whipworm infection and IL-10 signalling defects." (PMID 30640950, 2019). "During whipworm infection IL-10 signalling on cells of haematopoietic origin is critical for both the development of a type-2 response resulting in worm expulsion, and the control of type-1 immunity-driven inflammation and pathology." (PMID 30640950, 2019). "Outgrowth of opportunistic bacteria contributes to the mortality of IL-10 mutant mice during whipworm infection." (PMID 30640950, 2019). "Upon whipworm infection, we also observed augmented levels of ferritin and transferrin, which are indicators of systemic infection, in IL-10 signalling-deficient, but not in WT mice." (PMID 30640950, 2019). "In summary, our findings indicate that IL10 signalling, via the IL-10Rα and IL-10Rβ, promotes resistance to colonization by opportunistic pathogens and controls immunopathology preventing microbial translocation and lethal disease upon whipworm infection." (PMID 30640950, 2019). "The actions of IL-10 signalling on the control of type-2 and -1 responses during whipworm infections may depend on the timing, cell type and organ where IL-10 is produced and the receptor is expressed." (PMID 30640950, 2019). "Although a role of IL-22 in inducing goblet cell hyperplasia and promoting microbiota homeostasis during whipworm infections cannot be excluded, the induction of this mechanism of worm expulsion in the T. muris model is strongly dependent on the actions of IL-13 and regulated by IL-10." (PMID 30640950, 2019). "There is also little understanding on how these receptors can promote resistance to colonisation by opportunistic members of the microbiota that potentially drive the pathology observed in the absence of IL-10 during whipworm infection." (PMID 30640950, 2019). "Conditional knockout mice lacking IL-10Rα on T cells and monocytes/macrophages/neutrophils did not recapitulate the phenotype of the complete mutant, thus suggesting that these cell types alone are not the main responders to IL-10 during whipworm infection." (PMID 30640950, 2019).